PLAU (plasminogen activator, urokinase)
Description:
Serine protease that cleaves the inactive precursor plasminogen at a specific Arg-Val peptide bond, converting it into active plasmin. Secreted as an inactive zymogen, it is recruited and activated at the cell surface through interaction with the urokinase plasminogen activator receptor (uPAR). Cell-surface activation enables localized, plasmin-dependent pericellular proteolysis, regulating extracellular matrix degradation in cell migration and tissue remodeling. Also contributes to fibrinolysis and blood clot clearance by promoting plasmin generation (By similarity).
Synonyms: uPA; URK; ATF; BDPLT5; QPD; u-PA
Tractability: Small molecule: a structure with a bound ligand is known; a high-quality ligand is known; it has a high-quality binding pocket; it belongs to a druggable protein family. Antibody: UniProt places it where antibodies can reach, with high confidence; its Gene Ontology location is reachable by antibodies, with high confidence; UniProt predicts a signal peptide or a membrane-spanning region. PROTAC: ubiquitination databases record sites on it; a small molecule that binds it is known. Other modalities: an approved drug acts on it.
Target class: Serine protease; Enzyme; Serine protease PA clan; Serine protease S1A subfamily; Protease
Gene: Protein-coding gene on chromosome 10 (73,909,177 to 73,917,501, forward strand). Ensembl gene ENSG00000122861.
Subcellular location: Secreted
Subcellular location (Human Protein Atlas): Golgi apparatus; Vesicles; Predicted to be secreted
Pathways (Reactome):
Hemostasis: Dissolution of Fibrin Clot
Immune System: Neutrophil degranulation
Gene Ontology:
Molecular function: protein binding; receptor ligand activity; serine-type endopeptidase activity
Biological process: plasminogen activation; positive regulation of cell migration; positive regulation of epidermal growth factor receptor signaling pathway; positive regulation of extracellular matrix disassembly; regulation of cell adhesion; regulation of cell adhesion mediated by integrin; regulation of integrin-mediated signaling pathway; regulation of smooth muscle cell migration; regulation of smooth muscle cell-matrix adhesion; chemotaxis; fibrinolysis; negative regulation of fibrinolysis; negative regulation of plasminogen activation; proteolysis; regulation of fibrinolysis; regulation of plasminogen activation; regulation of wound healing; signal transduction; urokinase plasminogen activator signaling pathway
Cellular component: cell surface; extracellular exosome; extracellular region; focal adhesion; protein complex involved in cell-matrix adhesion; serine protease inhibitor complex; serine-type endopeptidase complex; external side of plasma membrane; plasma membrane; specific granule membrane; tertiary granule membrane
Genetic constraint (gnomAD): Loss-of-function variants: 33 observed, 51.8 expected, observed/expected ratio (o/e) 0.64, 90% interval 0.48 to 0.85. The upper end of that interval is the gene's LOEUF score, 0.85, which puts it in group 3 of 6, group 1 being the genes least tolerant of losing a copy. Missense variants: 455 observed, 572.01 expected, observed/expected ratio (o/e) 0.8, 90% interval 0.74 to 0.86. Synonymous variants: 199 observed, 218 expected, observed/expected ratio (o/e) 0.91, 90% interval 0.81 to 1.03.
Gene-disease validity (ClinGen):
ClinGen rates the evidence that PLAU causes each of these diseases.
Quebec platelet disorder (autosomal dominant): Moderate. Quebec platelet syndrome (QPS) is a platelet granule disorder characterized by moderate to severe bleeding after trauma, surgery or obstetric interventions, frequent ecchymoses, mucocutaneous bleeding and muscle and joint bleeds.
Homologues: Orthologues: chimpanzee PLAU (99% identical), macaque PLAU (93% identical), rabbit PLAU (83% identical), pig PLAU (81% identical), dog PLAU (78% identical), guinea pig PLAU (72% identical), rat Plau (71% identical), mouse Plau (69% identical), zebrafish plaub (38% identical). Paralogues in human: PRSS3 (23% identical), PRSS2 (23% identical), PRSS1 (23% identical).
Diseases named in the same sentence as PLAU in open-access papers:
PLAU is named in the same sentence as 181 diseases in open-access papers, as found by Europe PMC text mining. Sharing a sentence is not in itself a finding about the gene and the disease. The quoted sentences say what the papers report.
breast carcinoma (86 papers, 1993 to 2026). "In breast cancer, elevated PLAU expression levels are closely associated with prognosis, invasiveness, metastasis, and tumor infiltration." (PMID 40860340, 2025). "Based on the increased risk of metastasis that is associated with these functions, the oncogenic role of PLAU in several cancers, including breast cancer, has long been suggested." (PMID 36672610, 2022). "In breast cancer patients, increased levels of PLAU were associated with a worse prognosis and an increase in aggressiveness, metastasis, and invasion." (PMID 36672610, 2022). "PLAU upregulation is associated with an increase in aggressiveness, metastasis, and invasion of several cancer types, including breast cancer." (PMID 36672610, 2022). "We identified and validated several known metastasis mediators as regulated by MMP9, including Foxq1 and PLAU, as well as the suspected breast cancer susceptibility gene BRIP1." (PMID 24811362, 2014). "Our results are consistent with a previous study where PLAU overexpression promotes breast cancer cell growth." (PMID 38229120, 2024). "The higher expression of PLAU is regarded as a poor prognostic marker in aggressive breast cancer, hepatocellular carcinoma, and gastric cancer." (PMID 38363001, 2024). "In this study our aim was to test the oncogenic activity of PLAU in breast cancer cells, and to obtain further insight into PLAU as a potential therapeutic target in oncology." (PMID 36672610, 2022). "In conclusion, modulation of PLAU expression affected metastatic related properties of breast cancer cells, thus further validating its oncogenic activity in breast cancer cells." (PMID 36672610, 2022). "These clinical findings have led to the investigation of PLAU as a biomarker for predicting breast cancer prognosis and responsiveness to hormonal agents such as endocrine therapy." (PMID 36672610, 2022). "These clinical findings have led to the examination of PLAU as a biomarker for predicting breast cancer prognosis and therapy responses." (PMID 36672610, 2022). "In this study, we investigated the functional ability of PLAU to act as an oncogene in breast cancers by modulating its expression using CRISPR-deactivated Cas9 (CRISPR-dCas9) tools." (PMID 36672610, 2022). "HPR, PKLR and PLAU have been reported to be overexpressed in breast cancers and esophageal squamous cell carcinoma." (PMID 35327967, 2022). "We recognized a positive correlation between PSMC2 and PLAU, which plays a crucial role in the metastatic process of breast cancer." (PMID 34244472, 2021). "IHC analysis using anti-PLAU antibody in clinical specimens also visualized the upregulation of PLAU in breast cancer." (PMID 34244472, 2021). "Given the link between PSMC2 and PLAU, we next determined the mechanism of PLAU upregulation by PSMC2 in breast cancer." (PMID 34244472, 2021). "Previous studies revealed that PLAU is an oncogene in multiple cancers, including colorectal cancer, pancreatic cancer, breast cancer." (PMID 34696681, 2021). "The heat map shows the significant correlations between ERO1 and PERK, EIF2 alpha, VEGFA, SERPINE1, PLAU, TFRC and MMP1 in basal tumors, confirming the strong association of ERO1 with the PERK branch of UPR and angiogenesis in basal breast cancer." (PMID 33531624, 2021). "Emerging evidence implies that PLAU plays a critical role in the initiation and development of various cancers including breast cancer, colorectal cancer, and esophageal cancer." (PMID 33520474, 2021). "It has been found that PLAU is overexpressed in many types of human cancers, including breast cancer." (PMID 34244472, 2021). "Our results showed that PSMC2/PLAU axis promoted the tumorigenesis and development of breast cancer." (PMID 34244472, 2021). "Using complementary molecular approaches in multiple cellular models in vivo and in vitro, we demonstrated that PSMC2 plays an important role in tumorigenesis and the development of breast cancer through the regulation of PLAU signaling." (PMID 34244472, 2021).
breast carcinoma (continued). "Mesupron and nimbolide are PLAU inhibitors with potential for luminal A breast cancer treatment in vitro." (PMID 32947901, 2020). "We have previously shown the SAM-mediated methylation changes at the promoter of PLAU in breast cancer." (PMID 29435170, 2018). "PLAU (urokinase plasminogen activator gene, uPA gene) is a top correlated gene, which can enhance multiple oncogene expression in breast cancer." (PMID 29340066, 2017). "Following data mining in multiple big databases confirmed a positive correlation between SDC1 mRNA expression and PLAU mRNA expression in breast cancer tissues." (PMID 29340066, 2017). "In breast carcinoma cells, Int6 depletion induces diminished proliferation, decreasing urokinase-type plasminogen activator (PLAU) and apoptotic regulator BCL-XL, and favors epithelial-to-mesenchymal transition increasing Snail and Zeb2 expression." (PMID 24481065, 2014). "As PLAU is known to play an important role in breast cancer cell migration, it was investigated whether inducing PLAU expression alone was indeed sufficient to provoke functional changes in MCF-7 cells." (PMID 36672610, 2022). "Knockdown or overexpression of PLAU could enhance or alleviate the inhibition of PSMC2 depletion on breast cancer development." (PMID 34244472, 2021). "Outcomes of our study showed that overexpression of PSMC2 provide tumorigenic and metastatic advantages in breast cancer, which may involve the regulation of PLAU." (PMID 34244472, 2021). "These included urokinase plasminogen activator (PLAU) a well characterized prognostic and predictive marker for breast cancer invasion, the cell adhesion metallopeptidase ADAM8, implicated in tumor-progressive degradation of ECM proteins, and a pro-inflammatory cytokine, TNFSF12." (PMID 24498382, 2014). "Moreover, mice with knockout PLAU gene demonstrated slower growth and fewer metastases of human xenografted breast cancer cells in immunodeficient mice." (PMID 22842551, 2012). "Notably, C7, MMP13, and PLAU have been reported as promoters of breast cancer progression." (PMID 41150812, 2025). "Collectively, we deduced that PSMC2 may regulate breast cancer through PLAU." (PMID 34244472, 2021). "In conclusion, based on results of our GSEA analysis and knowledge from clinical trials we suggest the highest potential of alisertib and mesupron for CDK2 and PLAU-targeted therapy of lymph node negative luminal A breast cancer patients with high risk of distant metastasis." (PMID 32947901, 2020). "However, the PLAU knockdown only partially inhibited breast cancer cell migration and invasion." (PMID 27307030, 2016). "Conversely, an increase in PLAU expression was obtained in non-invasive, hormone-sensitive, ΕRα positive luminal A MCF-7 breast cancer cells by dCas9-VP64-sg TSSall leading to a higher migratory capacity of the cells." (PMID 36672610, 2022). "Both PLAU and SERPINE1 were found to be highly expressed in breast cancer patients with adjuvant endocrine therapy and related to shorter disease-free survival and OS." (PMID 36203433, 2022). "We also observed upregulation of FN1, PLAU and ALCAM in patients at most stages of breast cancer compared to expression in healthy individuals." (PMID 34641959, 2021). "When evaluated in a clinical cohort, we observed significant increase in expression of FN1, PLAU and ALCAM in patients with most subtypes of breast cancer compared to healthy volunteers." (PMID 34641959, 2021). "We found that FN1, PLAU and ALCAM were upregulated in patients with most subtypes of breast cancer compared to expression in healthy volunteers." (PMID 34641959, 2021). "When evaluated in clinical datasets, overexpression of FN1, PLAU, and ALCAM was observed in patients with different subtypes of breast cancer." (PMID 34641959, 2021). "The input features are the corresponding genes of well-established breast cancer biomarkers (ESR1, PGR, ERBB2, MKI67, PLAU) and the hybrid ensemble approach's final selected genes." (PMID 34290286, 2021).
breast carcinoma (continued). "Gene set analysis revealed that in human breast cancer cell lines the expression of these seven genes (MUC1, PLAU, FABP7, SPARC, HAS2, HAS3, SOX4) are higher in basal-B subtype compared to other subtypes." (PMID 29435170, 2018). "Our data show that SID peptide downregulates Wnt/β-catenin reporter activity and direct Wnt target genes (LEF1, TCF7L2, CD44, PLAU, MT1-MMP, MMP9, HMGA2) involved in breast cancer invasion and metastasis." (PMID 29179446, 2017). "In summary, NLN expression was directly regulated by miR-193a-5p, and CCND1, PLAU, and SEPN1 expression was directly regulated by miR-193a-3p in breast cancer cells." (PMID 27307030, 2016). "Knockdown of CCND1, PLAU, SEPN1, and NLN suppressed cell growth, similar to miR-193a-5p and miR-193a-3p overexpression in breast cancer cells." (PMID 27307030, 2016). "In this study, we demonstrated that miR-193a-3p suppressed breast cancer cell growth by directly inhibiting CCND1, PLAU and SEPN1 expression, and suppressed breast cancer cell migration/invasion via silencing PLAU." (PMID 27307030, 2016). "Seven over-expressed breast cancer genes, namely BCAR1, HSD17B1, MMP14, PLAU, SFRP2, SPP1 and VCAN, had increased promoter methylation and their promoters contained the tumor-specific hypermethylated A-6 or A-7 HMRs." (PMID 25706888, 2015). "Interestingly, the knockdown of PLAU along with MMP9, which is also FRA-1-regulated in breast cancer, restores the cell–cell adhesion and inhibits the expression of EMT-associated genes in BCCs." (PMID 37176013, 2023). "Therefore, herein, the cooperative effects of PLAU and PSMC2 on the development and progression of breast cancer were illustrated." (PMID 34244472, 2021). "As PLAU inhibitor, PAI1 is directly involved in extracellular matrix remodeling and cell adhesion, promoting tumor progression and metastasis in several cancers, including breast cancer." (PMID 30791886, 2019). "Furthermore, NLN and CCND1, PLAU, and SEPN1 were directly targeted by miR-193a-5p and miR-193a-3p, respectively, in breast cancer cells." (PMID 27307030, 2016). "Also, 7 genes (CTGF, ESR1, MAPK3, PIK3R3, PLAU, PRNP, and RET) were reported to be highly relevant to growth (P<1E-04) and microtubule dynamics (P<4E-05) in tumor cell lines, and apoptosis in breast cancers (P<1E-04)." (PMID 23185353, 2012). "In addition, BD inhibits expression of pro-metastastic genes PLAU and CXCR4, in breast cancer xenografts." (PMID 22842551, 2012). "siRNA knockdown of PLAU decreased in vitro TNBC-endothelial cell interactions and ex vivo extravasation of MDA-MB231 mono-clusters, revealing a potential role for CAF-induced factors expressed in TNBC cells, such as uPA/PLAU, in breast cancer cell extravasation." (PMID 42234219, 2026). "More importantly, cell lines with mere PSMC2 knockdown (shPSMC2+Vector), mere PLAU overexpression (PLAU + shCtrl), or simultaneous PSMC2 knockdown and PLAU overexpression (shPSMC2+PLAU) were constructed for further demonstrating the synergistic effects of PSMC2 and PLAU on breast cancer development." (PMID 34244472, 2021). "Studies have also demonstrated that knockdown of vimentin resulted in downregulation of genes involved in breast cancer invasion and the basal-like phenotype, including Axl, ITGB4, and PLAU, with a subsequent upregulation in the genes abundant in normal mammary epithelium, including RAB25 and EHF." (PMID 34769002, 2021).
prostate carcinoma (29 papers, 2012 to 2025). A carcinoma that arises from epithelial cells of the prostate gland. "Another proteolytic enzyme, PLAU, was downregulated in 3xR cells, and it is another activator of prostate cancer cell invasion and metastasis." (PMID 37870957, 2023). "Recently, RNA-seq data from prostate cancer cells overexpressing HMOX1 showed that HMOX1 down-modulated the PLAU pathway related to cell adhesion and cell-cell communication." (PMID 31527696, 2019). "The role of PLAU in promoting metastasis has been demonstrated in a previous study showing that knockdown of PLAU decreased the migration and invasion of prostate cancer cells." (PMID 27391090, 2016). "The identification of potential biomarkers such as APRT, CCL2, BEX2, MGC26963, and PLAU through specific gene modules and key genes could enhance our perception of prostate cancer's molecular mechanisms and targeted treatments." (PMID 38970097, 2024). "In prostate cancer and laryngeal squamous cell carcinoma, PLAU gene amplification was preferentially found in advanced stage, but not detected in benign lesions, suggesting PLAU may have a tumour stage-dependent expression pattern." (PMID 31443700, 2019). "Prostate cancer cells secrete BMP1, IGF, PDGF, vascular endothelial growth factor (VEGF), endothelin 1 (EDN1), plasminogen activator urokinase (PLAU) and kallikrein-related peptidase 3 (KLK3; also known as PSA), which regulate osteoblast proliferation or differentiation." (PMID 31753020, 2019). "Furthermore, it also inhibits the metastatic behavior of the human prostate cancer cells by inhibiting cell adhesion, invasion, and invasion, by downregulating of the expression of the CAV1, NR2F1, PLAU, and IGF2 genes and suppressing the secretion of urokinase plasminogen activator." (PMID 35046810, 2021). "Indeed, by knocking down PHF19L, we observed significant induction of multiple genes known to promote changes in cytoskeleton and adhesion, extracellular matrix remodeling, invasion, and metastasis in prostate cancer (including SOX9, SOX4, MMP1, PLAU, EPCAM, CXCR4, LOX, and MET)." (PMID 32155117, 2020).